SIRT4 (sirtuin 4)
Diseases named in the same sentence as SIRT4 in open-access papers (continued):
Sharing a sentence is not in itself a finding about the gene and the disease.
tumor (continued). "SIRT4 was also reported as a tumor suppressor or promoting protein in different tumors, involving in tumor cell proliferation, migration, invasion and metastasis." (PMID 37407961, 2023). "The immunostaining intensity of SIRT4 in the tumor tissue was notably lower than in the adjacent non-neoplastic prostate tissues." (PMID 35842463, 2022). "Loss of SIRT4 activates MAT2A, thereby increasing SAM level and dynamically regulating gene expression, which triggers the high proliferation rate of tumour cells." (PMID 36371321, 2022). "SIRT4 has been found to exhibit tumor suppressive role by virtue of its metabolic regulatory activity." (PMID 35842463, 2022). "While Sirt3 and Sirt4 have been identified as tumor suppressors, Sirt5 has been reported to be a tumor promoter in various types of cancer." (PMID 35963851, 2022). "The purpose of constructing a xenograft tumor mouse model was to understand the function of SIRT4 in vivo." (PMID 35847357, 2022). "Here, we investigated the role of mTORC1-c-Myc-SIRT4 axis in the regulating methionine metabolism by using tumour derived cell lines, mouse models and human specimens." (PMID 36371321, 2022). "Cellular treatment with FIDAS-5, an inhibitor of MAT2A, strongly affected MAT2A activity and its related histone methylation, as well as cell proliferation and tumour growth, similar to that observed in cells stably overexpressing SIRT4." (PMID 36371321, 2022). "We found that the tumor lumps in the SIRT4 overexpression group were markedly lower than that in the control group." (PMID 35847357, 2022). "In prostate cancer, the most diagnosed male cancer in industrialized society, where different environmental factors concur to its high incidence, SIRT4 affirms its role as tumor suppressor." (PMID 35328633, 2022). "Of these 85 pair of clinical samples, compared to matched normal liver tissues, a significant increase in the steady level of c-Myc protein but a reduced expression level of SIRT4 in tumour samples." (PMID 36371321, 2022). "In contrast, SIRT4 overexpression with combination of MR treatment greatly reduced the cell proliferation, migration, sphere formation abilities and tumour size, and prolonged mouse survival." (PMID 36371321, 2022). "Recent studies indicate that mitochondrial SIRT4 exhibits tumor-suppressing activities by promoting genomic stability." (PMID 35842463, 2022). "In our study, we demonstrated that the expression of SIRT4 in DTC tissues was downregulated, and its expression was associated with tumor progression." (PMID 35136826, 2022). "Further, SIRT4 overexpression inhibits the proliferation ability of HeLa cells, and SIRT4 knockdown in MEF cells inhibits large tumor development in nude mice in vivo." (PMID 35842463, 2022). "Consistently, the tumour growth was strongly inhibited by SIRT4 overexpression but increased in the mice injected with MAT2A-E111A mutant." (PMID 36371321, 2022). "Consistent with in vitro observations, SIRT4 ablation in mice displayed a more remarkable effect in the promotion of tumour formation in the control set and significantly decreased the life of these mice." (PMID 36371321, 2022). "SIRT4 exerts its tumour suppressive function with targeted therapy (sorafenib) by affecting methionine, redox and nucleotide metabolism." (PMID 36371321, 2022). "Accumulating evidence has demonstrated that SIRT4 suppresses tumor progression by inhibiting glutamine metabolism." (PMID 35847357, 2022). "SIRT4 is generally believed to be a tumor suppressor in many human malignancies as the tumor loses its expression." (PMID 34335684, 2021). "Recently, sirtuin 4 (SIRT4), a novel molecular has turned out to be related to alternating glutamine metabolism and modulating the tumor microenvironment." (PMID 34135317, 2021). "As reported, SIRT4 displays tumor suppressor activity through downregulating glutamine metabolism in several cancer types, which deserves further probe in ccRCC cells." (PMID 34135317, 2021).
tumor (continued). "Given SIRT4, the mitochondrial-localized sirtuin that inhibits GDH, we investigated the expression of SIRT4 in tumor and paracancerous of ccRCC patients." (PMID 34135317, 2021). "Sirtuin 4 (SIRT4), a mitochondrial protein, has been demonstrated to play a tumor-suppressive role in many cancers, including HCC." (PMID 33931611, 2021). "The tumor-suppressive role of SIRT4 has recently been suggested in many types of tumors including HCC26–30,32." (PMID 33931611, 2021). "Normal liver biopsies had a significantly higher SIRT4 mRNA expression than HCC tumor tissues and their peritumor tissues (both p < 0.0001)." (PMID 33931611, 2021). "Intriguingly, the HCC tumor tissues had a higher SIRT4 expression than their non-tumor counterparts." (PMID 33931611, 2021). "As reported, SIRT4 acts as a tumor suppressor by repressing proliferation, migration, and invasion ability of ccRCC cells." (PMID 34135317, 2021). "Taken together, SIRT4 enhanced ROS generation, while refuses HO-1 upregulation, which was meaningful for modulating the tumor microenvironment." (PMID 34135317, 2021). "It is indicated the tumor-promoting effect of C-MYC, GS, and GDH and tumor-inhibiting function of SIRT4." (PMID 34916485, 2021). "Collectively, overexpression of SIRT4 remarkably restrained cell survival and altered tumor hypoxic microenvironment." (PMID 34135317, 2021). "In recent years, SIRT4, as a mitochondrial protein 33, has attracted increasing attention for its role in regulating tumor energy metabolism." (PMID 33033517, 2020). "Most studies on the involvement of Sirt4 in tumor biology highlight this enzyme as a mitochondrion-localized tumor suppressor due to its crucial regulatory role of mitochondrial metabolism during tumorigenesis." (PMID 32373514, 2020). "Meanwhile, several lines of evidence indicate that SIRT4, which is localized in mitochondria, acts as a tumor suppressor." (PMID 32522234, 2020). "Here, we review the structure, localization, and enzyme activity of SIRT4 and its role in various neoplasms." (PMID 33585187, 2020). "The low expression of SIRT4 in various tumor tissues has been reported, which is closely correlated to poor prognosis 28, 31-34." (PMID 32194820, 2020). "In a study of 75 patients with gastric adenocarcinoma in 2015, SIRT4 expression in tumor tissue was significantly lower than that in corresponding normal tissues." (PMID 33585187, 2020). "Two mechanisms have been proposed by which SIRT4 inhibits tumorigenesis and tumor development, as studied in MEFs." (PMID 33585187, 2020). "SIRT4 expression in the peripheral tissues of HCC tumors was negatively correlated with tumor size, pathological grading, stage T, and clinical stage." (PMID 33585187, 2020). "The tumors developed in MMTV-neu; SIRT4-/- mice showed high tumor formation and lung metastasis compared to control models." (PMID 32863939, 2020). "In “normal” conditions, Sirt4 can inhibit tumor proliferation via the repression of the mitochondrial glutamine catabolism and the subsequent reduction of tumor metabolism." (PMID 32373514, 2020). "When DNA damage occurs in cells, SIRT4 expression is increased, and it stops glutamine metabolism, blocks the cell cycle, and inhibits tumor formation." (PMID 32194820, 2020). "Further studies thus are necessary to define the role of Sirt4 and the exact mechanisms involved in the balance between anti-stress (anti-apoptosis) and tumor inhibition (pro-apoptosis) under different pathophysiological and pharmacological conditions." (PMID 32373514, 2020). "Consistent with a role for SIRT3 and SIRT4 as tumor suppressor proteins, knock-out mouse lines for SIRT3 and SIRT4 develop mammary and lung tumors, respectively." (PMID 32846968, 2020). "Jeong and colleagues found that several types of neoplasms were incurred in ~63% (22/35) of SIRT4-KO animals, whereas 24% (6/25) of wild-type (WT) littermates had tumors." (PMID 33585187, 2020).
tumor (continued). "SIRT4 expression in peritumoral tissue of HCC patients was negatively correlated with tumor size, pathology grade, T stage, and clinical stage." (PMID 33585187, 2020). "SIRT4 level was negatively correlated with tumor size, pathological grading, tumor invasion depth, number of positive lymph nodes, and UICC stage." (PMID 33585187, 2020). "Our data on the centrosomal localization of SIRT4 and a putative SIRT4-microtubule dynamics axis are rather consistent with an additional extramitochondrial tumor suppressor function of SIRT4." (PMID 32846968, 2020). "Our previous studies have clarified the tumor-suppressive role of SIRT4 in HCC via mediating glutaminolysis." (PMID 32863939, 2020). "SIRT4 expression in ccRCC was lower than that in normal tissues, and low SIRT4 expression was obviously involved with poor overall survival and advanced tumor stage in ccRCC patients." (PMID 33585187, 2020). "IHC analyses showed that SIRT4 expression was down-regulated significantly in tumor tissues compared with that in paracancerous tissues." (PMID 33585187, 2020). "As one of the least studied sirtuin family members, the mitochondrial sirtuin SIRT4 is a tumor suppressor gene in various cancers." (PMID 32863939, 2020). "For these reasons, Sirt4 repression of mitochondrial glutamine catabolism by the inhibition of GDH activity seems to contribute significantly to its function as a tumor suppressor." (PMID 32373514, 2020). "In vivo evidence from mouse xenografts injected with the double knockdown cells revealed that the ablation of SIRT1 expression counteracted the effects of SIRT4 decline on tumor growth, which is consistent with the IHC data of Ki67 staining." (PMID 32863939, 2020). "Compared to normal liver tissues, SIRT1 (p = 0.002), SIRT2 (p = 0.01), and SIRT4 (p = 0.045) were significantly up-regulated in tumor tissues." (PMID 33093847, 2020). "In contrast, in “extreme” DNA-damaging conditions, including chemotherapy, Sirt4 can protect tumor cells, allowing them to escape apoptotic death and, potentially, to acquire more mutations and become more aggressive." (PMID 32373514, 2020). "In line with previous evidence, SIRT4 overexpression disrupted the proliferation, colony formation, and xenograft tumor formation of MDA-MB-231 cells, while ablation of SIRT4 caused the opposed effects on MCF-7 cells." (PMID 32863939, 2020). "In vivo evidence from mouse xenografts injected with transformed cells with or without EX-527 treatment revealed that SIRT1 inhibition counteracted the effects of SIRT4 decline on tumor growth." (PMID 32863939, 2020). "Meanwhile, Sirt4 has shown to be downregulated in many cancer types and appears to modulate tumor cell metabolism and adopts a tumor suppressor role colorectal cancer, Myc-induced B cell lymphoma and also in esophageal squamous cell carcinoma." (PMID 32698385, 2020). "Recently, several studies have shown that SIRT4 acts as a tumour suppressor in vitro and in vivo by regulating glutamine metabolism." (PMID 31447696, 2019). "We found that SIRT4 expression in CD68+ TAMs from tumours with grades III–IV was much lower than that from tumours with grades I–II." (PMID 31744516, 2019). "SIRT4 seems to have tumour suppressive activity induced by multiple genotoxic agents, and SIRT4-dependent inhibition of mitochondrial glutamine metabolism is necessary for the proper implementation of cell DNA damage response program." (PMID 31447696, 2019). "There are reports that SIRT4 functions as a tumor suppressor, restraining the growth and proliferation of cells." (PMID 31817470, 2019). "A recent study evaluated the role of SIRT4 with oncogenic or tumour-suppressive activity in cancer, suggesting that inhibiting metabolism and regulation of genome stability DNA were two possible mechanisms for the role of SIRT4 in tumours." (PMID 31447696, 2019).
tumor (continued). "Further studies are needed to determine the role of SIRT4 in the balance between anti-stress (anti-apoptosis) and tumour inhibition (pro-apoptosis) under different physiological conditions and the exact mechanism involved." (PMID 31447696, 2019). "A low expression level of SIRT4 is negatively correlated with tumor size, pathological grade, and lymph node metastasis and predicts a poor prognosis." (PMID 31817470, 2019). "SIRT4 was significantly downregulated in HCC tumour tissues, and the expression of SIRT4 in peritumour tissues was positively associated with survival in patients." (PMID 31744516, 2019). "We used HeLa cells because there is evidence for the involvement of Sirt4 as a tumor suppressor in cancer." (PMID 31817668, 2019). "The conclusion of these results is that SIRT4 expression is significantly downregulated in HCC tumour tissues." (PMID 31744516, 2019). "Immuno-histochemical staining showed that SIRT4 was downregulated significantly in tumour tissues compared with matched surrounding tissues." (PMID 31744516, 2019). "SIRT4 acts as a tumour suppressor of tumour growth by regulating cell metabolism, inflammation, and anti-tumourigenesis." (PMID 31744516, 2019). "This study suggested that SIRT4 was significantly downregulated in HCC tumour tissues and that the expression of SIRT4 in HCC peritumour tissues was positively associated with HCC survival." (PMID 31744516, 2019). "TMA and IHC results suggested that the expression of SIRT4 in HCC tumour tissue was significantly decreased compared to that in the matched peritumour tissues." (PMID 31744516, 2019). "Next, we further investigated SIRT4 expression in CD68+ macrophages from tumours with different grades." (PMID 31744516, 2019). "SIRT4 is necessary for the regulation of FAO in normal cells but is also identified as a mitochondrial-localized tumor suppressor." (PMID 30666234, 2018). "SIRT4 has been recognized to possess tumor-suppressive effects due to the crucial regulatory role of mitochondrial metabolism in tumourigenesis." (PMID 30666234, 2018). "In this review, we summarize the roles of SIRT4 in cellular metabolic homeostasis, including the regulation of insulin secretion and fatty acid oxidation and the effect on tumor cells of different tissues." (PMID 30666234, 2018). "Nevertheless, SIRT4 downregulation has been reported in several tumours, like bladder, gastric and breast cancer." (PMID 30356832, 2018). "SIRT4 possesses a tumor suppressive effect because of its inhibitory effect on glutamine catabolism and its antiproliferative effect on cells with DNA damage." (PMID 30666234, 2018). "The mitochondrial sirtuin SIRT4 acts as metabolic tumor suppressor and is down-regulated in many cancer types." (PMID 31225445, 2017). "A similar decrease in SIRT4 expression was also observed in larger tumor (T3–T4, p<0.005) as compared to smaller tumors (T1–T2)." (PMID 26785117, 2016). "SIRT3 and SIRT4 are tumor suppressor genes and the primary mitochondrial deacetylase which regulates metabolic function through variety of mechanisms." (PMID 26785117, 2016). "Recently, SIRT4 has been suggested as a tumor suppressor by regulating DNA damage response pathways." (PMID 24019980, 2013). "While SIRT3, SIRT4, and SIRT6 are poised to induce tumor-suppressive autophagy, others, such as SIRT2 and SIRT7, are likely to stimulate protective autophagic programs that underlie tumor survival and drug resistance." (PMID 41425553, 2025). "By contrast, SIRT2 and SIRT4 support cytotoxic anti-tumor immunity." (PMID 41425553, 2025). "SIRT4 may have both oncogenic and tumor suppressor effects in cancers, although the mechanisms of action remain unclear." (PMID 41304967, 2025).
tumor (continued). "A similar tumor suppressor activity is seen for SIRT4 in CRC as well." (PMID 41425553, 2025). "However, 10 μM acetyl-CoA was neither able to enhance H3K27 acetylation, nor to promote stem cell-like properties, while forced expression of SIRT4 in α2δ1+ cells resulted in retardation of tumor growth in vivo." (PMID 40384857, 2025). "Among these, SIRT1, SIRT4, and SIRT5 are the most highly implicated regulators, exhibiting both tumor-suppressive and tumor-supportive functions, depending on the cellular and tumor context." (PMID 41425553, 2025). "As a tumor suppressor, SIRT4 inhibits glutamine metabolism in mitochondria of tumor cells." (PMID 38773972, 2024). "Additionally, SIRT4 emerges as a critical tumor suppressor in PDAC, with its regulatory role extending across mitochondrial metabolism, cellular proliferation and cancer progression." (PMID 39682281, 2024). "Conversely, the downregulation of SIRT4 in non-tumorous cells led to the accumulation of cellular mutations and subsequent tumor formation." (PMID 38702756, 2024). "SIRT4 emerges as a tumor suppressor in various cancers, evidenced by multiple studies." (PMID 38773972, 2024). "Thus, we propose an additional extra-mitochondrial function of SIRT4 as a cytosolic tumor suppressor of C-RAF-MAPK signaling, besides its metabolic tumor suppressor role of glutamate dehydrogenase and glutamate levels in mitochondria." (PMID 38499327, 2024). "In some cancers, SIRT4-induced autophagy can suppress tumor growth, while in others, it may contribute to survival under adverse conditions." (PMID 39682281, 2024). "However, SIRT4 negatively regulates these oncogenic processes, inhibiting glycolysis, cell proliferation and tumor expansion." (PMID 39682281, 2024). "For instance, strategies aimed at restoring the tumor-suppressive functions of SIRT3 or enhancing SIRT4 activity could reverse metabolic reprogramming and tumor survival mechanisms." (PMID 39682281, 2024). "Specifically, in vitro cell culture experiments and in vivo transgenic and xenografted animal models revealed that SIRT4 could inhibit tumor growth and promote autophagy in PDAC." (PMID 36209169, 2023). "Current studies on SIRT4 in tumors prefer SIRT4 as a tumor suppressor, SIRT4 is a metabolism‐related factor with multiple enzymatic activities, and SIRT4 can inevitably have some effect on the malignant biological behavior of tumor cells by regulating the metabolism of tumor cells." (PMID 40625712, 2023). "An increasing number of studies have shown that SIRT4 is involved in tumor development." (PMID 37301821, 2023). "In other words, the overexpression of SIRT4 will reduce the energy obtained by the tumor." (PMID 36925927, 2023). "Functionally, SIRT4 has been characterized in mitochondria as tumor suppressor and inhibitor of the metabolic gatekeeper enzymes pyruvate dehydrogenase (PDH;) and glutamate dehydrogenase (GDH;) as well as based on its deacetylase activity as a regulator of leucine metabolism and insulin secretion." (PMID 37803520, 2023). "SIRT4 responds to changes in cellular nutrient availability by controlling energy metabolism, and in this way, SIRT4 plays an irreplaceable role in glucose metabolism, amino acid metabolism, and tumor therapy." (PMID 40625712, 2023). "In summary, the present study suggests that SIRT4 immunohistochemistry may be a reliable prognostic biomarker in BLCA and that SIRT4 plays the role of tumor suppressor in BLCA." (PMID 37301821, 2023). "Here, we review the progress of SIRT4 research in tumor metabolism and therapy." (PMID 40625712, 2023). "Our study reveals that SIRT4 plays a tumor suppressor role in BLCA." (PMID 37301821, 2023). "SIRT4 can suppress tumor activity by inhibiting mitochondrial GDH metabolism." (PMID 40625712, 2023). "Interestingly, SIRT4 has previously been reported to function as both a tumor oncogene and a tumor suppressor gene." (PMID 37301821, 2023).